IFNG (interferon gamma)
Diseases named in the same sentence as IFNG in open-access papers (continued):
Sharing a sentence is not in itself a finding about the gene and the disease.
glioblastoma (continued). "However, low expression levels of miR-329 correlate with survival in glioblastoma multiforme patients, studies of hippocampal neurons suggest it to be involved in dendritic outgrowth, and miR-329 expression is decreased in airway smooth muscle treated with IL-1β, TNFα, and IFNγ." (PMID 24143215, 2013). "Therefore, we believed that in glioblastoma, the overexpression of CCL5 enhances the NKκB and IFNγ signaling pathway of tumor-infiltrating T cells, leading to their exhaustion." (PMID 41155216, 2025). "Interestingly, we have recently shown that peripheral T and NK cells from glioblastoma patients display greater levels of TIM-3 and lower activity markers CD69 and IFNγ compared to T and NK cells from healthy individuals." (PMID 41516291, 2025). "However, we saw a significant reduction in the percentage of CD69 and IFNγ positivity in PMA and ionomycin-stimulated CD4+ and CD8+ T cells and NK cells from glioblastoma patients compared to their counterparts in healthy donors." (PMID 40072074, 2025). "However, a significantly reduced level of induction of IFNγ positivity was seen on stimulated CD4+ and CD8+ T cells and NK cells from glioblastoma patients." (PMID 39513882, 2024). "Blood-derived neutrophilic and eosinophilic MDSCs are further considered to suppress autologous non-specific T cell proliferation and IFNγ secretion leading to impaired anti-tumor immunity in glioblastoma patients." (PMID 36497232, 2022). "However, CXCR4-blockade in combination with anti-PD-1 has been shown to have a synergistic effect in increasing the proportion of IFNγ+ and TNFα+ producing CD4+ and CD8+ T cells in the brains of mice with glioblastoma." (PMID 35464424, 2022). "Other clinical trials for recurrent glioblastoma or gliosarcoma evaluated directly injected, genetically modified, conditionally replicative and oncolytic human-derived adenovirus, DNX-2401 in combination with IFNγ (NCT02197169)." (PMID 33790740, 2021). "A separate study has also reported that effective CAR T cell antitumor activity of IL13Ra2-CAR T cells against mouse syngeneic glioblastoma (GBM) is significantly dependent on the activation of patient-derived endogenous T cells and monocyte/macrophages at the tumor site in an IFNγ-dependent manner." (PMID 34721401, 2021). "Interestingly, we observed that penfluridol significantly suppressed human IFNγ in the tumor microenvironment in SCID-NOD mice injected with human PBMCs and implanted with human U87MG glioblastoma tumors." (PMID 28512255, 2017). "The basis of such an observation is not clear, however it is of interest that IFNγ-induced STAT1 activation has been previously shown to negatively regulate hypoxia-inducible factor-1 (HIF-1) α-dependent transcription in human glioblastoma cells lines." (PMID 27769057, 2016). "In addition, the data indicated that both the antiviral response to IFNγ and the contribution of ICP0 to viral escape from this response at high MOI vary between glioblastoma lines." (PMID 22924042, 2012). "Interestingly, cytokine secretion by CD276-targeted CAR NK-92 cells was more pronounced after co-incubation with non-malignant cell lines and K562 cells, whereas all glioblastoma cells only led to moderate TNFα and IFNγ secretion." (PMID 40469103, 2025). "Based on the data obtained in a syngeneic mouse glioblastoma, it has also been reported that CAR-T cells have the potential to establish crosstalk with the tumor microenvironment, essential to promoting endogenous anti-tumor immunity involving the in vivo production of IFNγ." (PMID 37173879, 2023). "Regardless of different data on IFNγ concentration changes, it could be used in combination therapy in cancer, including glioblastoma." (PMID 38003396, 2023). "Additionally, tumor cells including glioblastoma cells have been reported to express IDO without IFNγ induction." (PMID 22924042, 2012).
fungal infections (124 papers, 2010 to 2026). "This loss of function was linked to reduced levels of IFNγ and IL-17, indicating a failure in the activation of the Th1/Th17 response, which is essential in controlling fungal infections." (PMID 40422691, 2025). "Th1 is shown to be prevalent in eliminating fungal infection in healthy hosts, which is associated with increased levels of interleukin (IL)-2, IL-12, and interferon-gamma (IFN-γ)." (PMID 39330416, 2024). "IFNγ is a hallmark cytokine of Th1 immune responses, which are crucial for combating intracellular fungal infection." (PMID 38904363, 2024). "Genetic defects in the capacity to produce or respond to interferon-gamma (IFN-γ) have been the IEI most frequently reported associated with TDEF mycoses." (PMID 36986378, 2023). "GM-CSF deficiency impairs the production of TNFα and IFNγ, which are important for the control of intracellular fungal infections." (PMID 36177012, 2022). "Genetic deficiencies in the NADPH oxidase system (phox) manifest as chronic granulamatous disease, while deficiencies in IFNγ activity lead to increased susceptibility to bacterial and fungal infections, particularly with mycobacteria." (PMID 19925904, 2010). "Many of these cytokines, such as IFNγ, TNFα, GM-CSF, IL-6, IL-17a, and GRO-α, are associated with protection against fungal infections." (PMID 38469300, 2024). "Memory T-cells are instrumental in the secretion of cytokines, such as interferon-gamma (IFN-γ) and interleukin-17 (IL-17), which aid in recruiting and stimulating other immune cells to counter the fungal infection." (PMID 38143753, 2023). "Based on their cytokine secretion and functions during fungal infections, T cells are classified into Th1 (IFNγ, GM-CSF, and TNFα), Th17 (IL-17A/F), Th22 (IL-22), Th2 (IL-4 and IL-13), Th9 (IL-9 and IL-10), Treg (IL-10 and TGFβ), and Tr1 (IL-10)." (PMID 36177012, 2022). "Cytokines used as immunomodulatory agents in fungal infection include colony-stimulating factors (CSFs), Interferon-Gamma (IFN-γ), TNF α and Interleukins." (PMID 33042859, 2020). "IFNγ plays an important role in host defense against several fungal infections, and exogenous IFNγ has been proposed as an adjunctive therapy to accelerate fungal clearance." (PMID 30283457, 2018). "CD4+ and CD8+ T-cells, NK cells, γδT cells, and neutrophils have been shown to produce IFNγ during fungal infection." (PMID 29403476, 2017). "In a previous study we have identified that IFNγ treatment had beneficial effects on the immune status including IL-17 and IL-22 responses in a case series of patients with invasive fungal infections." (PMID 25888308, 2015). "The first attractive application of immunomodulating to treat invasive fungal infections is the treatment with certain cytokines, for example, IFNγ/GM-CSF to improve antigen presentation and thus to enhance immune defense against fungal pathogens." (PMID 23401680, 2013). "Our assertion may not be limited to H. capsulatum because monocyte‐derived cells and IFNγ responsiveness are proven to be crucial in multiple other fungal infections including Aspergillus, Candida, Cryptococcus, and Blastomyces species." (PMID 35603470, 2022). "Severe COVID-19 disease is associated with an increase in pro-inflammatory markers, such as IL-1, IL-6, and tumor necrosis alpha, less CD4 interferon-gamma expression, and fewer CD4 and CD8 cells, which increase the susceptibility to bacterial and fungal infections." (PMID 34036149, 2021). "However, the delicate balance of IL10/IFNγ needs to be in check since high level of IL10 suppresses the activity of IFNγ which provides the main Th1 defense against fungal infections." (PMID 26635780, 2015). "M1 macrophages are induced by bacterial compounds or pro-inflammatory cytokines like IFNγ and have the capacity to increase and sustain the ongoing inflammatory response and to clear the system of bacterial, viral and fungal infections via production of inflammation-promoting mediators (e.g. IL-12)." (PMID 22558252, 2012).
fungal infections (continued). "In addition, severe COVID-19 causes an increase in proinflammatory mediators, such as IL-1, IL-6, and tumor necrosis factor-alpha (TNF-α), less CD4 interferon-gamma (INF-γ) expression, and fewer CD4 and CD8 cells, which enhance susceptibility to both bacterial and fungal infections inside the body." (PMID 36992139, 2023). "Based on pathophysiological mechanisms and limited pre-clinical and clinical data, adjunctive immune-stimulatory therapy with interferon-gamma (IFN-γ) may represent a promising candidate to improve outcome of invasive fungal infections by enhancing host defence mechanisms." (PMID 24669841, 2014). "Moreover, IFNγ is used as a prophylactic treatment of infection in patients with chronic granulomatous disease (CGD), a genetically inherited disease characterized by an increased susceptibility to fungal infections." (PMID 21533108, 2011). "In our model, we identified IFNγ (or) IL-17 secreting total CD4 + T cells and CD69 + activated CD4 + T cells that regulate fungal infection during C. auris reinfection." (PMID 40294061, 2025). "Cytokine secretion (mainly interferon-gamma (IFN-γ) and TNF-α) has been demonstrated as one of the main effector mechanisms through which CD8+ T-cells can restrict fungal infection." (PMID 38404288, 2024). "In a fungal infection with physiological conditions, the IL-17a pathway downregulated the Trp catabolism and completely antagonized the induction IDO1 by interferon-gamma (IFN-γ) in neutrophils." (PMID 37048160, 2023). "In simple words, at the time of fungal inoculation, being on FTY720 for at least two days hindered the IFNγ response of the mice to the disseminating fungal infection, while initiating FTY720 in later timepoints did not." (PMID 36477491, 2022). "The role of CD8+ T-cells in the direct killing of fungi has been established and cytokine secretion (mainly interferon gamma [IFN-γ] and TNF-α) has been demonstrated as one of the main effector mechanisms through which CD8+ T-cells can restrict fungal infection." (PMID 34696267, 2021). "In contrast to the altered fate exhibited by Th17 cells during EAE where erstwhile Th17 cells cease IL-17A expression and gain IFNγ expression, acute fungal infection with C. albicans gives rise to Th17 cells that do not deviate to IFNγ-producers." (PMID 28408906, 2017). "Nine days after infection, Mst1ΔDC mice displayed significantly attenuated pathological kidney injuries, less fungal survival in the kidney and higher serum IL-17 production, but not IFNγ production, indicating that MST1 signalling is required for precipitating the fungal infection in DCs." (PMID 28145433, 2017).
pulmonary fibrosis (124 papers, 2007 to 2025). Chronic progressive interstitial lung disorder characterized by the replacement of the lung tissue by connective tissue, leading to progressive dyspnea, respiratory failure, or right heart failure. "In mice lungs, Ccl5 is produced after bleomycin instillation, associated with the influx of Ccr5+ IFNγ-producing γδ T cells, attenuating lung fibrosis in Ackr2-/- mice." (PMID 39768150, 2024). "A relative deficiency in IFNγ mRNA expression was associated with progressive lung fibrosis in IPF patients." (PMID 20302663, 2010). "Finally, to confirm the mode of action of γδ T cells to decrease bleomycin-induced pulmonary fibrosis, they infused IFNγ+ γδ T cells into IFNγ-deficient mice." (PMID 36403186, 2023). "Within the adaptive immune system, there is some evidence that CD4+ Th1, Th2, and Th17 subtypes may play role in pulmonary fibrosis and their plethora of cytokines such as interferon gamma (IFN-γ) for Th1 and IL-4 and IL-13 for Th2 cells have been linked to disease development in the lung." (PMID 24454287, 2014). "Meanwhile, genes exhibiting ASE-Gain in pulmonary fibrosis were enriched in aorta morphogenesis, response to interferon-gamma, negative regulation of cell growth, and other pathways related to lung vasculature, cell, and immunity." (PMID 40388309, 2025). "Given that IFNγ has been shown to ameliorate bleomycin-induced lung fibrosis in mice, we expected FINCA mice to be more prone to fibrosis." (PMID 40510178, 2025). "In the peripheral blood of SSc‐ILD patients, upregulated genes including S100A8, S100A12, ADAMTS2, IFNG, and SERPINB2 were identified, which have been linked to the progression of lung fibrosis." (PMID 40165483, 2025). "The lung tissue levels of IL-6, osteopontin, IFNγ, and SP-D were significantly lower in the TG group with lung fibrosis than in their WT counterparts." (PMID 39329706, 2024). "Elevated Ccl5 levels are associated with the influx of Ccr5+ IFNγ-producing γδ T cells, mitigating lethality and lung fibrosis in Ackr2-/- mice, revealing a potential role of CCL5 counterbalancing pulmonary fibrosis triggered by bleomycin." (PMID 39768150, 2024). "In previous studies, laboratory findings (including interleukin-6 (IL-6), LDH, interferon-gamma, and KL-6 levels) have been suggested to be prognostic factors for pulmonary fibrosis." (PMID 36233779, 2022). "IPF outcomes are worsened by treatment with low dose Prednisone, Azathioprine, and unaffected by treatment with biologics targeting interferon gamma or TNFα." (PMID 34434962, 2021). "Our study suggests that the effects of an AhR ligand, FICZ, on AhR led to increase the number of Tregs and reduced that of CD4+IFNγ+ T cells and contributed to alleviating lung fibrosis." (PMID 32033616, 2020). "In a bleomycin-induced pulmonary fibrosis model, IFNγ produced by γδ T cells was found to attenuate fibrosis by indirectly inhibiting IL-17-secreting Th17 cells." (PMID 32676074, 2020). "Our selection includes cytokines previously associated with the lung response to radiation in both mice and humans such as Il6 and Tnfα) as well as pulmonary fibrosis-promoting Il1β, Il13 and Il17) and anti-fibrotic mediators Il10 and Ifnγ." (PMID 25889053, 2015). "CXCL10/IP-10, which is regulated by the antifibrotic factor IFNγ, has been shown to attenuate bleomycin-induced pulmonary fibrosis in mice via inhibition of fibroblast recruitment or of angiogenesis." (PMID 20302663, 2010). "Iloprost prevents bleomycin-induced pulmonary fibrosis, possibly by upregulating antifibrotic mediators (IFNγ and CXCL10) and downregulating pro-inflammatory and pro-fibrotic cytokines (TNFα, IL-6, and TGFβ1)." (PMID 20302663, 2010). "It has been suggested that pirfenidone and interferon gamma, both ameliorate lung fibrosis by downregulation of PDGF expression." (PMID 17217530, 2007).
pulmonary fibrosis (continued). "A growing number of studies have shown that Th1 cells exert resistance to lung fibrosis by inducing an inflammatory response in the lung through the release of pro-inflammatory cytokines IL-2, interferon-gamma (IFN-γ), tumor necrosis factor(TNF), IL-12, and IL-18 production." (PMID 40433386, 2025). "Additionally, the BALF concentrations of TNFα, interleukin-6 (IL-6), osteopontin, interferon-γ (IFNγ), and SP-D were substantially lower in TG mice with lung fibrosis than in their WT counterparts." (PMID 39329706, 2024). "Increased levels of Ccl12 may drive the Ccr2+ IFNγ-producing γδ T cell, reducing pulmonary fibrosis triggered by bleomycin in Ackr2-/- mice." (PMID 39768150, 2024). "IFNγ seems to be necessary for the induction of fibrosis by bleomycin but the suppression of IFNγ-related genes was reported in fibroblasts from IPF and for patients with lung fibrosis associated with systemic sclerosis." (PMID 38255185, 2023). "NKT cells attenuate pulmonary fibrosis by producing IFNγ and reducing TGFβ levels." (PMID 32676074, 2020). "Il17 and Ifnγ have been reported to exert opposing effects on the development of pulmonary fibrosis and a predictive model based on their interaction supports the paradigm that fibrotic lung disease is the result of the synergy between various immune cell types and their cytokine repertoires." (PMID 25889053, 2015). "In addition, antagonizing LTB4 receptor attenuated the lung fibrosis induced by bleomycin in mice by suppressing the production of inflammatory and fibrotic cytokines and by promoting the antifibrotic cytokine, IFNγ." (PMID 20302663, 2010). "Furthermore, knocking IFNγ out not only alleviates inflammation but also attenuates lung fibrosis." (PMID 32033616, 2020). "In the lung tissues, IL-6, osteopontin, IFNγ, and MCP-1 levels were markedly increased in WT and TG mice with lung fibrosis compared to their respective saline-treated controls." (PMID 39329706, 2024). "IFNγ+CD4+ T cells in the lungs and IFNγ in bronchoalveolar lavage fluid are increased following intratracheal administration of BLM, culminating in lung fibrosis." (PMID 32033616, 2020). "The interest in these cells in lung fibrosis is due to their role in the regeneration of injured epithelia, in the metabolism of respiratory toxicants, and due to the secretion of CCSP, which modulates the activity of TGBβ and IFNγ in the distal airways." (PMID 38255185, 2023). "It should also be noted that the induced by P. agglomerans significant increase of concentration of antifibrotic cytokines, such as IL10, IL12 and IFNγ does not match the pulmonary fibrosis observed in the histological analysis." (PMID 33999928, 2021). "The extent of pulmonary fibrosis evident at respiratory distress was not correlated to lavage PMN in distressed Ifnγ−/− mice (correlation coefficient = −0.02)." (PMID 28912510, 2017). "Exogenous administration of IFNγ has been shown to be critical for limiting lung fibrosis in CXCR3 knockout mice lacking endogenous IFNγ." (PMID 20302663, 2010).